TRIM38 (tripartite motif containing 38)
Description:
E3 ubiquitin-protein and E3 SUMO-protein ligase that acts as a regulator of innate immunity. Acts as a negative regulator of type I interferon IFN-beta production by catalyzing 'Lys-48'-linked polyubiquitination of AZI2/NAP1, leading to its degradation (By similarity). Mediates 'Lys-48'-linked polyubiquitination and proteasomal degradation of the critical TLR adapter TICAM1, inhibiting TLR3-mediated type I interferon signaling. Acts as positive regulator of the cGAS-STING pathway by acting as a E3 SUMO-protein ligase: mediates sumoylation of CGAS and STING, preventing their degradation and thereby activating the innate immune response to DNA virus (By similarity). Also acts as a negative regulator of NF-kappa-B signaling independently of its E3 protein ligase activity by promoting lysosome-dependent degradation of TAB2 and TAB3 adapters.
Synonyms: RNF15; RORET
Tractability: Antibody: the Human Protein Atlas places it where antibodies can reach. PROTAC: ubiquitination databases record sites on it; its protein half-life has been measured.
Gene: Protein-coding gene on chromosome 6 (25,962,777 to 25,991,231, forward strand). Ensembl gene ENSG00000112343.
Subcellular location: Cytoplasm
Subcellular location (Human Protein Atlas): Centrosome; Cell Junctions; Plasma membrane
Pathways (Reactome):
Immune System: Interferon gamma signaling
Gene Ontology:
Molecular function: protein binding; transcription coactivator activity; ubiquitin protein ligase activity; zinc ion binding
Biological process: positive regulation of canonical NF-kappaB signal transduction; innate immune response; regulation of gene expression; regulation of viral entry into host cell; positive regulation of DNA-templated transcription; positive regulation of viral process; protein sumoylation; protein ubiquitination; regulation of viral life cycle
Cellular component: cytoplasm; cytosol
Genetic constraint (gnomAD): Loss-of-function variants: 33 observed, 36.87 expected, observed/expected ratio (o/e) 0.9, 90% interval 0.68 to 1.2. The upper end of that interval is the gene's LOEUF score, 1.2, which puts it in group 5 of 6, group 1 being the genes least tolerant of losing a copy. Missense variants: 542 observed, 579.85 expected, observed/expected ratio (o/e) 0.93, 90% interval 0.87 to 1. Synonymous variants: 198 observed, 216.31 expected, observed/expected ratio (o/e) 0.92, 90% interval 0.81 to 1.03.
Homologues: Orthologues: chimpanzee TRIM38 (99% identical), macaque TRIM38 (95% identical), pig TRIM38 (77% identical), dog TRIM38 (71% identical), rabbit TRIM38 (70% identical), mouse Trim38 (56% identical). Paralogues in human: TRIM6 (37% identical), TRIM21 (35% identical), TRIM68 (34% identical), TRIM5 (34% identical), TRIM11 (33% identical), TRIM22 (33% identical), TRIM39 (33% identical), TRIM58 (32% identical), TRIM34 (32% identical), TRIM60 (31% identical), TRIM27 (30% identical), TRIM61 (30% identical), and 68 more.
Diseases named in the same sentence as TRIM38 in open-access papers:
TRIM38 is named in the same sentence as 31 diseases in open-access papers, as found by Europe PMC text mining. Sharing a sentence is not in itself a finding about the gene and the disease. The quoted sentences say what the papers report.
viral infection (9 papers, 2011 to 2025). "TRIM38 overexpression upregulated the RIG-I/MDA5 pathway and promoted the level of IFN-β early during viral infection, while TRIM38 knockout had the opposite effect." (PMID 40006954, 2025). "Similar to the other TRIM family members, TRIM38 has been first reported to be a critical effector in the generation and development of viral infection and inflammatory diseases." (PMID 37116711, 2023). "Previous report indicates that TRIM38 has E3 ubiquitin ligase activity and can be degraded during virus infection, TRIM38 functions as an E3 enzyme and can be self-ubiquitinated." (PMID 37116711, 2023). "mcGAS was found to be SUMOylated by TRIM38 at the resting state on K271/K464, which antagonizes ubiquitination-mediated degradation, resulting in cGAS stabilization for acute sensing viral infection." (PMID 35795661, 2022). "To further figure out the associations between TRIM38 and GLUT1, we performed the lenti-virus infection technology to inhibit expression levels of GLUT1 in TRIM38-deficient cells." (PMID 34906161, 2021). "Our observations demonstrate that the expression of TRIM38 protein is regulated after viral infection." (PMID 21306652, 2011). "The precise role and mechanism of TRIM38 in ubiquitylation and virus infection need to be further addressed." (PMID 21306652, 2011). "Our observations demonstrate that TRIM38 has E3 ubiquitin ligase activity and can be degraded during virus infection." (PMID 21306652, 2011). "We propose that TRIM38 may exert bidirectional regulation on innate immune signaling in response to distinct viral infections or at different stages of infection." (PMID 40006954, 2025). "TRIM38 expression can be induced by Toll-like receptor (TLR) ligands, type I interferons (IFN-I), and viral infections, suggesting that TRIM38 may function as an interferon-stimulated gene (ISG)." (PMID 40006954, 2025). "The expression of TRIM38 protein is modulated by various viral infections." (PMID 40006954, 2025). "Therefore, we postulate that TRIM38 limits the excessive production of type I IFNs in response to viral infection by mediating degradation of TRIF." (PMID 23056470, 2012). "We also show that EV71 infection induces degradation of TRIM38 in the cells, suggesting that TRIM38 may play a role in viral infections." (PMID 21306652, 2011). "To examine whether TRIM38 expression is affected upon virus infection, we analyzed the TRIM38 expression level in response to EV71 infection." (PMID 21306652, 2011). "TRIM38 overexpression upregulates the RIG-I/MDA5 pathway and increases IFN-β levels early during viral infection." (PMID 40006954, 2025). "Overall, our findings show how TRIF is regulated by TRIM38 and provide new insight into the mechanism by which the TLR-mediated immune response is regulated over the course of viral infection." (PMID 23056470, 2012). "TRIM38 could upregulate the RIG-I/MDA5 pathway and promote the level of IFN-β early during viral infection." (PMID 40006954, 2025). "Additionally, TRIM38 has been shown to negatively regulate RIG-I activation, thereby modulating inflammatory responses during viral infections." (PMID 40162781, 2025). "Moreover, Trim38 expression can be induced by TLR ligands, IFNs-I, and viral infections, further supporting its involvement in antiviral immunity." (PMID 40362389, 2025). "Thus, TRIM38/SENP2 controls both cGAS and STING protein stability in the early and late stages of viral infection to ensure the timely activation and inactivation to fine-tune the pathway responses." (PMID 35795661, 2022). "Taken together, these findings indicate that EV71 infection reduces the TRIM38 expression at the protein level rather than at RNA level and that TRIM38 may play a role in virus infection." (PMID 21306652, 2011).
bladder cancer (6 papers, 2021 to 2025). "For instance, the expression of TRIM38 was shown to be low in bladder cancer, and it was inversely associated with overall survival and advanced clinical features." (PMID 38811952, 2024). "Lower expression of TRIM38 was linked to shorter survival rate and worse prognosis in patients with bladder cancer." (PMID 37215134, 2023). "Fourteen TRIM family proteins were associated with bladder cancer (tumor-promoting: TRIM9, TRIM25, TRIM26, TRIM28, TRIM29, TRIM59, TRIM65, and TRIM66; tumor-suppressive: TRIM19 and TRIM38)." (PMID 40723250, 2025). "Overexpression of TRIM38 inhibits the growth of bladder cancer via enhancing the ubiquitinoylation and degradation of GLUT1." (PMID 38811952, 2024). "In conclusion, we demonstrated that TRIM38 E3 ubiquitin ligase regulates GLUT1 protein stability through ubiquitin-dependent proteasomal degradation in bladder cancer cells." (PMID 34906161, 2021). "This study aimed to investigate the functional roles of TRIM38 in bladder cancer to identify effective targets." (PMID 34906161, 2021). "Recently, research demonstrated that TRIM38 interacts with GLUT1 to suppress the progression of bladder cancer, and another study revealed that TRIM38 regulates the AMPK/NF‐κB/NLRP3 pathway to inhibit the progression of lung cancer, gradually revealing the importance of TRIM38 in malignancy." (PMID 40047371, 2025). "According to TCGA bladder cancer database, TRIM38 expression was low in bladder cancer patients." (PMID 37215134, 2023). "TRIM38 was further found to regulate proliferation, stemness and invasion of bladder cancer cells." (PMID 37215134, 2023). "Other TRIM proteins (TRIM9, TRIM38, TRIM65, and TRIM66) promoted progression of bladder cancer by targeting GLUT1, ANXA2, and MMP11." (PMID 40723250, 2025). "Strikingly, TRIM38 had an interaction with GLUT1 and enhanced the ubiquitination and degradation of GLUT1 in bladder cancer cells." (PMID 37215134, 2023). "We constructed a prognostic model based on Necroptosis subtype-related prognosis DEGS by lasso algorithm and multivariate COX analysis, which consists of 6 predictors (CERCAM POLR1H, KCNJ15, GSDMB, EHBP1, TRIM38), among which CERCAM is closely related to bladder cancer." (PMID 35478725, 2022).
liver fibrosis (4 papers, 2023 to 2026). "The vicious cycle resulting from hepatocyte steatosis, insulin resistance, the inflammatory response, and liver fibrosis was aggravated by TRIM38 deficiency in hepatocytes." (PMID 37116711, 2023). "A mouse model of liver fibrosis induced by CCl4 was established in vivo to further evaluate the expression levels of fibrosis markers, including TRIM38." (PMID 42072369, 2026). "Hepatocytes lacking TRIM38 show heightened susceptibility to steatosis, insulin resistance, inflammation, and liver fibrosis." (PMID 37867509, 2023). "Some can play the same role in the face of the same disease, such as TRIM28 and TRIM38 in the progression of MAFLD and TRIM15 and TRIM47 in liver fibrosis." (PMID 39199424, 2024). "In a CCl4-induced mouse model of liver fibrosis, α-hederin (4 mg/kg) significantly reduced the liver index and serum ALT and AST levels, improved histopathological damage to the liver, upregulated TRIM38 expression in liver tissue, and inhibited the endoplasmic reticulum stress response (ERS)." (PMID 42072369, 2026). "TRIM38 directly binds to TAB2, and recognizes the K63 of RIP1 in the TNF-α signaling pathway through TAB2 to connect the ubiquitin chain or TRAF6 in the IL-1β signaling pathway, thereby inhibiting the key pathway TAK1-MAPK cascade in the process of liver fibrosis." (PMID 37867509, 2023).
autoimmune disease (3 papers, 2021 to 2025). A disorder resulting from loss of function or tissue destruction of an organ or multiple organs, arising from humoral or cellular immune responses of the individual to their own tissue constituents. "TRIM38 may be involved in the development of various autoimmune diseases and generally in the innate immune response." (PMID 34177938, 2021). "Notably, the interaction between TRIM38 and TAB2/3 is weakened in RA, resulting in an excess expression of TAB2/3 and proinflammatory cytokines, indicating the essential roles of TRIM38 in modulating autoimmune disease severity." (PMID 34177938, 2021). "TRIM38 has been shown to be capable of activating NF-κB signaling pathways and may participate in regulating innate immune response, various pathophysiological processes, such as bone proliferation, tumorigenesis, and autoimmune diseases." (PMID 37116711, 2023).
Autoimmunity (3 papers, 2019 to 2024). The occurrence of an immune reaction against the organism's own cells or tissues. "Of note, most of these patients were negative for other autoantibodies associated with autoimmunity and/or lung autoimmunity in other conditions (KCNRG, BPIFB1, TRIM38, CENP-A, interferon-ω, ABLIM, and CDHR) suggesting some specificity for ILD in the context of SjD." (PMID 39524452, 2024).
glioma (3 papers, 2021 to 2025). A benign or malignant brain and spinal cord tumor that arises from glial cells (astrocytes, oligodendrocytes, ependymal cells). "This study demonstrated that Zika virus (ZIKV) infection can promote the expression of TRIM38 in human glioma cells (U251)." (PMID 40006954, 2025). "Univariate analysis and multivariate analysis of the correlation of the expression of CDC20, UBE2C, WDR62, DTL, HOXB4 and TRIM38 with OS among glioma patients." (PMID 33914773, 2021). "Our results showed that 25 of the differentially expressed URGs were related to survival in glioma patients; six genes, CDC20, UBE3C, WDR62, DTL, HOXB4, and TRIM38, were statistically significant with an AUC value greater than 0.7." (PMID 33914773, 2021). "TRIM38, CCR5, PLAU, P2RY8, and PROS1 were upregulated in glioma tissues, while HAMP and S100A9 were downregulated." (PMID 34954691, 2021). "We observed that the IRSs of PROS1, P2RY8, PLAU, CHI3L2, MSR1, CCR5, and TRIM38 were higher than its corresponding IRSs in low-grade glioma, while the IRSs of HAMP, CARD16, and S100A8 in high-grade glioma were lower than low-grade glioma." (PMID 34954691, 2021). "The results showed that TRIM38, CCR5, PLAU, P2RY8, and PROS1 have a higher immunoreaction score (IRS) in tumors than normal tissues (p < 0.05), while the IRS of HAMP and S100A9 in gliomas were lower than normal tissues (p < 0.05)." (PMID 34954691, 2021).
ZIKV infection (2 papers, 2025). "Further characterizations showed that TRIM21 and TRIM14 act as restriction factors against ZIKV and LGTV, while TRIM38 hinders ZIKV infection." (PMID 40431659, 2025). "The results of quantitative RT-PCR showed that ZIKV infection significantly upregulated the transcription of TRIM38 in U251 cells." (PMID 40006954, 2025). "Our results showed that ZIKV infection markedly increased both the mRNA and protein levels of TRIM38 in U251 cells, and IFN-β upregulated TRIM38 expression in a dose-dependent manner, suggesting that TRIM38 may function as an ISG involved in the innate immune response against ZIKV." (PMID 40006954, 2025). "At 36 h post-ZIKV infection, the expression levels of interferon-induced antiviral proteins, including ISG15, ISG56, OAS1, OAS2, and OAS3, were increased by TRIM38 overexpression and decreased by TRIM38 knockout." (PMID 40006954, 2025). "In this study, TRIM38 overexpression in U251 cells increased the expression of RIG-I/MDA5 signaling pathway-related proteins, including RIG-I, MDA5, TBK1, and IRF3, at 6 h post-ZIKV infection, and also increased the IFN-β level." (PMID 40006954, 2025).
adenovirus infection (1 paper, 2023). "Since we proved that TRIM38 directly interacts with TAB2 and associates with its degradation, we overexpressed Tab2 via adenovirus infection in Trim38-overexpressed primary hepatocytes." (PMID 37116711, 2023). "Inversely, we overexpressed TRIM38 in primary hepatocytes by adenovirus infection and confirmed the protein level of Trim38 by WB." (PMID 37116711, 2023). "To further testify whether the effects of TRIM38 in NAFLD depends on TAB2, we overexpressed Tab2 via adenovirus infection in Trim38 overexpressed primary hepatocytes." (PMID 37116711, 2023).
breast carcinoma (1 paper, 2025). "TRIM38, an E3 ubiquitin-protein ligase, has previously been implicated in innate immune and inflammatory responses, yet its role in breast cancer regulation remains unclear." (PMID 41347593, 2025). "Both in vitro and in vivo experiments demonstrate that TRIM38 inhibits breast cancer proliferation, migration, and invasion." (PMID 41347593, 2025). "Collectively, the findings underscore TRIM38 as a crucial regulator of autophagy and present novel, promising therapeutic targets for breast cancer." (PMID 41347593, 2025). "This study elucidates the suppressive function of TRIM38 in breast cancer progression." (PMID 41347593, 2025). "The results indicate a decreased expression of TRIM38 in breast cancer tissues compared to adjacent non-cancerous counterparts, and its reduced expression correlates with unfavorable clinical outcomes in breast cancer patients." (PMID 41347593, 2025).
chronic hepatitis B (1 paper, 2025). "Studies found that TRIM38 expression was significantly increased in peripheral blood mononuclear cells (PBMCs) of HBeAg-negative chronic hepatitis B patients, suggesting a potential association with the early treatment effects of peg-IFN-α and HBsAg clearance." (PMID 40006954, 2025).
colorectal cancer (1 paper, 2025). A primary or metastatic malignant neoplasm that affects the colon or rectum. "This study reveals the tumor‐suppressive role of TRIM38 in colorectal cancer (CRC)." (PMID 40047371, 2025).
dermatomyositis (1 paper, 2021). Dermatomyositis (DM) is a type of idiopathic inflammatory myopathy characterized by evocative skin lesions and symmetrical proximal muscle weakness. "Similarly, in patients with dermatomyositis (DM, an autoimmune connective tissue disease characterized by erythema in the eyes and hands, and weakness in the proximal muscles), skin and muscle biopsy analyses showed that TRIM38 gene expression was upregulated." (PMID 34177938, 2021).
Flavivirus Infections (1 paper, 2025). Infections with viruses of the genus FLAVIVIRUS, family FLAVIVIRIDAE. "TRIM38 is one of the three TRIMs that were enriched during flavivirus infection." (PMID 40431659, 2025). "Altogether, these data suggest that TRIM38, TRIM21, and TRIM14 are ISGs that mediate the IFN-I response against flavivirus infection." (PMID 40431659, 2025). "From the screening, we identified the TRIM38, TRIM21, and TRIM14 proteins, which were enriched during flavivirus infection." (PMID 40431659, 2025). "To identify the role of TRIM38, TRIM21, and TRIM14 proteins during flavivirus infection, we made polyclonal A549 cells overexpressing these TRIMs." (PMID 40431659, 2025).
glucose metabolic disorder (1 paper, 2023). "In addition, compared with the control group, TRIM38 deficiency markedly enhanced the HFD-induced glucose metabolic disorder, as evidenced by the higher glucose levels under fasting conditions and increased AUC of GTTs compared with the control group." (PMID 37116711, 2023). "Similarly, TRIM38-KO aggravated the HFHC-induced glucose metabolic disorder, as evidenced by increased blood glucose levels, AUC in GTT." (PMID 37116711, 2023).
Hepatic steatosis (1 paper, 2023). Steatosis is a term used to denote lipid accumulation within hepatocytes. "Genetic Trim38-KO in vivo showed that TRIM38 depletion deteriorated the high-fat diet and high fat and high cholesterol diet-induced hepatic steatosis and high fat and high cholesterol diet-induced liver inflammation and fibrosis." (PMID 37116711, 2023). "Taken together, these results indicate that TRIM38 deletion exacerbates hepatic steatosis, inflammation, and fibrosis under metabolic stress." (PMID 37116711, 2023). "In summary, our study revealed that TRIM38 could suppress hepatic steatosis, inflammatory, and fibrosis in NAFLD via promoting transforming growth factor-β-activated kinase 1 binding protein 2 degradation." (PMID 37116711, 2023). "Moreover, histological staining of H&E, Oil Red O staining, CD11b, and Picrosirius red staining assays demonstrated that TRIM38 depletion exacerbated HFHC diet-induced hepatic steatosis, inflammation, and fibrosis." (PMID 37116711, 2023). "In addition, Trim38-KO mice exhibited exacerbated hepatic steatosis, as indicated by H&E and Oil Red O staining." (PMID 37116711, 2023). "We further proved that TRIM38 depletion aggravated the high-fat diet (HFD)- or high fat and high cholesterol (HFHC) diet-induced hepatic steatosis, inflammation, and fibrogenesis in mice." (PMID 37116711, 2023).
lentivirus infection (1 paper, 2021). Virus diseases caused by the Lentivirus genus. "Besides, stable BCLA cells with TRIM38 overexpression were also established via lentivirus infection, which were detected by western blot." (PMID 34906161, 2021).